MUC16 (mucin 16, cell surface associated)
Diseases named in the same sentence as MUC16 in open-access papers (continued):
Sharing a sentence is not in itself a finding about the gene and the disease.
ovarian carcinoma (continued). "In ovarian cancer, the selective overexpression of Mucin-16 (MUC16, CA125) in tumor cells highlights its potential as a promising target for developing anti-tumor therapies." (PMID 38637885, 2024). "We find that MSLN-CAR T cells effectively eliminate ovarian cancer tumor cells and stem-like cells in vitro, and this cytotoxic function is dependent on high expression levels of MUC16 on the tumor cell membrane." (PMID 38637885, 2024). "MUC16 is a massive and highly glycosylated cell surface protein present in large amounts on the surface of almost all ovarian cancer cells." (PMID 38225646, 2024). "Nectin-4 had a higher sensitivity and specificity compared to the MUC16 standard biomarker, especially for early-stage ovarian cancer." (PMID 40836974, 2024). "Our findings showcase the potential for CAR T-cell therapies based on mesothelin that can treat ovarian cancer and other MUC16-positive malignancies." (PMID 38637885, 2024). "MUC16 is not only expressed in normal tissues, but also plays a role in various diseases, especially ovarian cancer and pancreatic cancer." (PMID 38758220, 2024). "An accurate molecular model of CA125 (MUC16) will support these efforts and is hoped to bring the realization of improved molecular tools for ovarian cancer management into being." (PMID 38197671, 2024). "The expression of MUC16 in OCSC has been identified as the primary source of tumor metastasis and recurrence, and our study has confirmed the ability of MSLN-CAR T cells to recognize and eliminate CSCs derived from ovarian cancer cell lines that express MUC16." (PMID 38637885, 2024). "In fact, several mucins are currently used as biomarkers in the clinic, as MUC1 (CA15-3) in breast cancer and MUC16 (CA125) in ovarian cancer." (PMID 38384845, 2024). "The intracellular 4-1BB and CD3ζ protein domains were shown to be activated in T-cells when MSLN296-359 bound successfully to MUC16 on ovarian cancer cells." (PMID 40836974, 2024). "MUC16 can manipulate glucose uptake by controlling GLUT1 in epithelial ovarian cancer cells, thus promoting glycogen synthesis, so that tumor cells produce more energy for proliferation." (PMID 39219440, 2024). "Given the significance of MUC16 in ovarian cancer treatment, the study of immunotherapies and clinical trials demands special attention." (PMID 38361923, 2024). "In the case of ovarian cancer, research indicates that Mucin‐16 (MUC16) and Mesothelin (MSLN) are significant tumour antigens, presented respectively by human leukocyte antigen‐I and human leukocyte antigen‐II molecules." (PMID 38613345, 2024). "MUC16 is another common target for platinum-resistant ovarian cancer treatment evaluated in two completed phase I trials (NCT01335958 and NCT02146313)." (PMID 38539161, 2024). "Approximately 80% of ovarian cancers exhibit MUC16 expression, which is present in all ovarian cancer subtypes (including serous, mucinous, endometrioid, and clear cell) though it varies in expression." (PMID 38361923, 2024). "MUC16 plays a significant role in ovarian cancer research, with its relationship to tumor growth, metastasis, and chemotherapy resistance extensively supported by research." (PMID 38361923, 2024). "Exposure to ascites, the fluid accumulating in the abdominal cavity during advanced disease, increases the expression of MUC16 in mesothelial cells in vitro MUC16 encodes for CA125, a biomarker for ovarian cancer progression." (PMID 37545408, 2023). "We then explored the correlation between MUC16 and inflammation and key inflammatory cells in ovarian cancer according to TCGA Ovarian Cancer dataset with GSVA." (PMID 37644468, 2023). "MUC16 (mucin 16, also known as CA-125) is a known biomarker for ovarian cancer, which has been shown to play a role in enabling tumor growth and metastasis in many tumors." (PMID 37215143, 2023).
ovarian carcinoma (continued). "It is important to note that the constitutive expression and secretion of MUC16 by mesothelial cells is several-fold higher than other cell types, including ovarian cancer cells." (PMID 36816942, 2023). "One other biomarker, also found to be wanting, is Mucin-16, also known as ovarian cancer-related tumor marker CA125 (MUC-16), a transmembrane glycoprotein that is overexpressed in pancreatic cancer." (PMID 37606420, 2023). "Since IL-6, IL-8, PD-L1, IDO and ROS have been shown to inhibit the killing function of NK cells, we treated NK-92 cells with the supernatant of MUC16- treated neutrophils and evaluated the ability of NK-92 to kill ovarian cancer cell line OVCAR-3." (PMID 37644468, 2023). "Considering the results of OCOs stimulation, we assumed that MUC16 expressed by ovarian cancer altered neutrophils’ immunophenotype." (PMID 37644468, 2023). "Ubamatamab (REGN4018) is a human bispecific antibody that binds mucin 16 (MUC16), a glycoprotein highly expressed in ovarian cancer cells, and the CD3 receptor on T cells, with the goal of inducing T-cell activation to kill ovarian cancer cells." (PMID 38248092, 2023). "To overcome this limitation, we describe an engineered cell with both dual targeting and orthogonal cytotoxic modalities directed against two tumor antigens that are highly expressed on ovarian cancer cells: cell surface Muc16 and intracellular WT1." (PMID 37214945, 2023). "MUC16 acted on neutrophils by Siglec-9 leading to an inflammatory and immunosuppressive phenotype in ovarian cancer." (PMID 37644468, 2023). "Our study found positive correlations between the serum MUC16 levels and the number of neutrophils and the inflammatory factors in ovarian cancer patients, indicating that MUC16 was correlated to the inflammatory and immune microenvironment." (PMID 37644468, 2023). "Since then, CA125/MUC16 has become the most significant biomarker for ovarian cancer diagnosis, surveillance of disease progression, and recurrence." (PMID 37670245, 2023). "CAR-T cells have also been generated to target MUC16 TAA, showing the specific killing of MUC16+ ovarian cancer cells in vitro and delayed tumor development or fully eradicated disease in vivo." (PMID 38067396, 2023). "The described examples reinforce the usefulness of employing the analysis of MUC16 aberrant glycoforms to improve the clinical performance of MUC16 as a biomarker for ovarian cancer." (PMID 37455827, 2023). "Our model ligand/analyte pairs were two ovarian cancer biomarker proteins (MUC16 and HE4) and their corresponding monoclonal antibodies." (PMID 37571487, 2023). "For instance, CA125, also called MUC16, is one of the biomarkers implemented for the diagnosis of ovarian cancer and is currently being investigated for other malignancies." (PMID 36980526, 2023). "Siglec-9, the receptor of MUC16, was expressed on neutrophils and was positively correlated to neutrophil infiltration in ovarian cancer." (PMID 37644468, 2023). "In conclusion, our study found that MUC16 induced an inflammatory response in neutrophils, which promotes the development of a systemic hyperinflammatory state in ovarian cancer patients." (PMID 37644468, 2023). "The level of STn-MUC16 discriminated patients with endometriosis and with ovarian cancer, with 44% sensitivity and 100% specificity." (PMID 37455827, 2023). "In another study, a sandwich ELISA was developed to measure the level of STn antigen expressed on MUC16, which allowed to differentiate between patients with endometriosis and ovarian cancer." (PMID 37455827, 2023). "Mesothelin is a crucial regulator in the multistep process of ovarian cancer peritoneal spread, which is stimulated by MUC16 via binding to mesothelial cells, allowing tumor cells to adhere to mesothelial cells." (PMID 37664708, 2023). "The interaction of MUC16 with mesothelin leads to peritoneal metastasis of ovarian cancer cells by facilitating the attachment of cancer cells to the mesothelial lining." (PMID 36559316, 2022).
ovarian carcinoma (continued). "Bispecific CAR-T cells targeting PD-L1 and MUC16 have an enhanced killing effect on ovarian cancer cells and significantly prolong the survival time of tumor-bearing mice." (PMID 36428765, 2022). "For instance, prostate-specific antigen (PSA) in prostate cancer, carcinoma antigen 125 (CA125/MUC16) in ovarian cancer, CA19-9 and carcinoembryonic antigen (CEA) in colon cancer, and aberrantly glycosylated MUC1 (also known as CA15-3) in breast cancer." (PMID 36338982, 2022). "Cancer antigen 125 (CA-125) is a mucin-like glycoprotein, also known as mucin 16 (MUC-16), used to monitor epithelial ovarian cancer." (PMID 35590912, 2022). "MUC16 encodes a protein also known as ovarian carcinoma antigen CA125, which is clinically recommended as a screening biomarker for ovarian cancer." (PMID 36199046, 2022). "Regarding ovarian carcinoma (OvCa), Mucin-16 (MUC16) and Mesothelin (MSLN) were recently described as the top HLA class I- and HLA class II-presented tumor antigens, respectively." (PMID 35565389, 2022). "It is produced by the MUC16 gene and is the most widely used tumor marker for clinical detection of ovarian cancer." (PMID 35663045, 2022). "Serum carbohydrate antigen 125 (CA125), encoded by MUC16, is the most valuable FDA-approved biomarker for ovarian cancer." (PMID 36564848, 2022). "Measurement of serum CA125, an antigenic fragment of human mucin 16 (MUC16), is used to monitor the clinical progression of epithelial ovarian cancer (EOC)." (PMID 35219339, 2022). "Some studies have reported that MUC16 is a potential target for antibody therapy against ovarian cancers." (PMID 35628495, 2022). "MUC16 is overexpressed in 80% of epithelial ovarian cancer (EOC) and 65% of pancreatic ductal adenocarcinomas (PDAC), where effective ‘theranostic’ probes are much needed." (PMID 36559316, 2022). "Ubamatamab (REGN4018) is a bsAb-based T-cell engager against CD3 and MUC16 that is used for the treatment of patients with advanced ovarian cancer." (PMID 35628495, 2022). "We selected NK cells to correlate with details of the patient’s clinical course because of the previous work describing MUC16 inhibition of synapse formation between NK cells and ovarian cancer tumor cells, thus preventing NK-cell tumoricidal function." (PMID 35219339, 2022). "In pancreatic cancer, combined chemo-immunotherapy with anti-MUC16 led to the development of specific T-cell immunity while targeting MUC16 revealed prolonged progression-free and OS in a Phase II study in advanced ovarian cancer." (PMID 36230626, 2022). "MUC16 is overexpressed in ovarian cancer and contributes to ovarian-cancer progression and metastasis." (PMID 35628495, 2022). "CA125, an extracellular domain of MUC16, is a serological biomarker for treatment monitoring and recurrence of ovarian cancer." (PMID 35836956, 2022). "Carbohydrate antigen 125 (CA-125) and mucin 16 (MUC16) is a glycoprotein found in ovarian cancer cells that can be used in the diagnosis of ovarian cancer." (PMID 36015143, 2022). "Along with ovarian cancer, the mucin MUC16 is highly overexpressed in more than 60% of PDAC tumors and significantly worsens disease progression in this highly lethal malignancy." (PMID 36686742, 2022). "As a biomarker for ovarian cancer, MUC16 has been extensively used, and its expression has been shown to be related with the course of the disease." (PMID 36051359, 2022). "The MAb Oregovumab and vaccines targeting MUC16 have been investigated among patients with ovarian cancer." (PMID 35389164, 2022). "The phase I dose-escalation study of DMUC4064A, an innovative ADC drug that targets MUC16 expressed in the ovarian cancer cell, was completed in 2021." (PMID 35795565, 2022). "Monocytic and NK cell Siglec-9 was found to strongly interact with STn antigen containing MUC16 to mediate immunosuppression in ovarian cancer and exacerbate prognosis." (PMID 36686742, 2022).
ovarian carcinoma (continued). "In the field of ovarian cancer research, the biomarker MUC16 (which was formerly known as CA125) has been employed extensively, and its expression has been found to be related with the course of the disease." (PMID 36051359, 2022). "MUC16 is a member of the mucin family glycoprotein, which has been used as a tumor marker in the early diagnosis of ovarian cancer and other tumors." (PMID 33867349, 2021). "The ectopic expression of the c-terminal domain of MUC16 induces cisplatin resistance in ovarian cancer cells." (PMID 34681277, 2021). "Propofol inhibited ovarian cancer cell proliferation, glycolysis metabolism, migration and invasion, which were partly recovered by circ_MUC16 overexpression." (PMID 34837947, 2021). "The expression of MUC16 increases ovarian cancer cell motility, invasiveness, and metastatic properties and enhances tumor growth and metastases of ovarian cancer in SCID mice." (PMID 33613114, 2021). "In 1981, a high molecular weight protein expressed on the surface of ovarian cancer cells was recognized by a monoclonal antibody selectively targeting MUC16, and it was subsequently found to be elevated in the sera of ovarian cancer patients." (PMID 34150633, 2021). "Since MUC16 is known to be overexpressed on the surface of ovarian cancer cells and cleaved/shed into blood, it is a well-established serum biomarker for ovarian cancer." (PMID 34681277, 2021). "Validation of our MUC16ecto- BiTEDs expands the scope of MUC16-directed immunotherapy and sets the foundation for combinatorial strategies in ovarian cancer." (PMID 33936101, 2021). "These antibodies were tested in a cytotoxicity assay aimed at killing the PSMA + prostate cancer cell line C4-2 or the MUC16 + ovarian cancer cell line OVCAR-3 in the presence of human PBMCs." (PMID 34257348, 2021). "MUC16, or CA125, is a highly evaluated tumour biomarker that is elevated in ovarian cancer and is linked with disease progression." (PMID 34830751, 2021). "The objective of this study was to explore the role of circular RNA mucin 16 (circ_MUC16) in Propofol-mediated inhibition of ovarian cancer." (PMID 34837947, 2021). "To assess oncolytic activity in vivo, we tested Ad5/MUC16-1040/TK-EGFP in an ovarian cancer xenograft mouse model using NOD-scid IL2Rgammanull (NSG) immunodeficient mice." (PMID 34503075, 2021). "Collectively, our study findings suggest that the development of CRAd targeting MUC16/CA-125 represents a unique and practical approach to ovarian cancer treatment." (PMID 34503075, 2021). "The MUC16 protein is a heavily glycosylated member of the mucin family with normal Mullerian tissue expression and is overexpressed on High Grade Serous Epithelial Ovarian Cancer cells (HGSOC)." (PMID 33936101, 2021). "The mucin MUC16 (or CA125) is mostly known as a biomarker in ovarian cancer and is used to monitor patients as an indicator of cancer recurrence." (PMID 33643374, 2021). "Success in developing a CRAd that can only replicate in and lyse cancer cells expressing CA-125 provides proof-of-concept that transactivation of MUC16/CA-125 can be targeted for ovarian cancer treatment." (PMID 34503075, 2021). "Ovarian cancer cell-derived MUC16 induces an attenuated cytotoxic activity of human NK cells with phenotypic alterations." (PMID 34681277, 2021). "We also determined E1A expression levels via Western blot in selected ovarian cancer cell lines infected with Ad5/MUC16-1040/TK-EGFP." (PMID 34503075, 2021). "Collectively, these data indicate that targeting MUC16 transactivation utilizing CRAd is a feasible approach for ovarian cancer treatment that warrants further investigation." (PMID 34503075, 2021). "We found that the silencing of Gal3 in MUC16-expressing breast and ovarian cancer cells in vitro inhibited tumor cell invasion and led to attenuated tumor growth in murine models." (PMID 33580170, 2021).
ovarian carcinoma (continued). "Our data indicate that targeting MUC16 transactivation for ovarian cancer treatment by conditionally replicative oncolytic virus development is practical and warrants further investigation." (PMID 34503075, 2021). "Circ_MUC16 overexpression alleviated the effects of Propofol to promote the aggressive behaviors of ovarian cancer by targeting the miR-1182/S100B network." (PMID 34837947, 2021). "TNF-α and IFN-γ increase MUC16 expression in breast, endometrial, and ovarian cancers via NF-κB-mediated transcription regulation." (PMID 34681277, 2021). "For translational purposes, we tested the Ad5/MUC16-1040/TK-EGFP on primary ovarian cancer cells collected from two patients; case 1 was from pleural effusion, and case 2 was from ascites." (PMID 34503075, 2021). "Our data manifested that circ_MUC16 expression was significantly elevated in ovarian cancer, and Propofol treatment notably depleted circ_MUC16 expression in ovarian cancer cells." (PMID 34837947, 2021). "The study in ovarian cancer also showed that MUC16 binds selectively to mesothelin, a glycoprotein normally expressed by the mesothelial cells of the peritoneum." (PMID 34150633, 2021). "MUC16, a sialomucin that contains the ovarian cancer biomarker CA125, binds at low abundance to leucocytes via the immune receptor, Siglec-9." (PMID 33922973, 2021). "Investigations also approved the research importance of MUC16 as a potential target for ovarian cancer cell treatment." (PMID 33494834, 2021). "CA125/MUC16 has high prognostic value for post therapy follow-up but has poor sensitivity for diagnosing ovarian carcinomas in the early stages." (PMID 34555499, 2021). "The infiltration of CD8+ T cells was indicated to be significantly lower in MUC1-high tumors (BRCA, GBM, LGG, PAAD, THYM, and UCEC) and MUC16-high ovarian cancer, which was assessed by several prediction algorithms." (PMID 34681277, 2021). "These MUC16ecto- BiTEDs retain binding in the presence of soluble MUC16 (CA-125) and show cytotoxicity against a panel of ovarian cancer cells in vitro." (PMID 33936101, 2021). "Mucin 16 (MUC16) is a glycosylated mucin widely expressed in ovarian cancer, serving as a promising target for CAR-T therapy." (PMID 34386017, 2021). "MUC16 codes for a mucin, which is commonly shed in ovarian cancer and less frequently in other tumors of epithelial origin." (PMID 34944094, 2021). "Malignant ascites contains a milieu of pro-inflammatory factors that can contribute to ovarian cancer growth, metastasis, and the release of mucin 16 (MUC16), which is involved in ovarian cancer tumorigenesis and metastasis." (PMID 34503128, 2021). "Two CD28-targeting BsAbs were developed, one for ovarian cancer (MUC16 × CD28) and another for prostate cancer (PSMA × CD28, REGN5678)." (PMID 34358141, 2021). "MUC16-expressing ovarian cancer cells can bind specifically to the MSLN-expressing peritoneal lining to further peritoneal implantation." (PMID 32780245, 2020). "These include those from cultured cells (MUC1 from breast cancer and chronic myelogenous leukaemia cell lines, and MUC16 from a cervical cell line), and ascites from ovarian cancer patients." (PMID 32937961, 2020). "MUC16 is a known selectin ligand, and it regulates ovarian cancer growth, tumorigenesis, and metastasis." (PMID 32785160, 2020). "MUC16 is overexpressed on the surface of ovarian cancer and PDA cells and is also present on the mesothelial cells lining the peritoneum." (PMID 32780245, 2020). "Perhaps the most easily recognizable one in the context of ovarian cancer is mucin 16 (MUC16), also known as cancer antigen 125, which is the serum biomarker used to monitor ovarian cancer patients." (PMID 32785160, 2020).